SCRT1 (scratch family transcriptional repressor 1)
Description:
Transcriptional repressor that binds E-box motif CAGGTG. Can modulate the action of basic helix-loop-helix (bHLH) transcription factors, critical for neuronal differentiation.
Synonyms: SCRT; DKFZp547F072; ZNF898
Tractability: No criterion of Open Targets' tractability assessment is met for any kind of drug.
Gene: Protein-coding gene on chromosome 8 (144,330,565 to 144,336,482, reverse strand). Ensembl gene ENSG00000261678.
Subcellular location: Nucleus
Subcellular location (Human Protein Atlas): Nuclear bodies
Gene Ontology:
Molecular function: DNA-binding transcription repressor activity, RNA polymerase II-specific; RNA polymerase II transcription regulatory region sequence-specific DNA binding; sequence-specific DNA binding; sequence-specific double-stranded DNA binding; DNA-binding transcription factor activity; DNA-binding transcription factor activity, RNA polymerase II-specific; RNA polymerase II cis-regulatory region sequence-specific DNA binding
Biological process: negative regulation of transcription by RNA polymerase II; regulation of DNA-templated transcription; regulation of transcription by RNA polymerase II
Cellular component: nuclear body; nucleus
Genetic constraint (gnomAD): Loss-of-function variants: 3 observed, 3.46 expected, observed/expected ratio (o/e) 0.87, 90% interval 0.38 to 1.8. That is too few expected variants to judge how well the gene tolerates losing a copy. Missense variants: 375 observed, 434.46 expected, observed/expected ratio (o/e) 0.86, 90% interval 0.79 to 0.94. Synonymous variants: 238 observed, 193.61 expected, observed/expected ratio (o/e) 1.23, 90% interval 1.11 to 1.37.
Homologues: Orthologues: chimpanzee SCRT1 (100% identical), macaque SCRT1 (99% identical), mouse Scrt1 (93% identical), pig SCRT1 (93% identical), rat Scrt1 (93% identical), dog SCRT1 (93% identical), guinea pig SCRT1 (93% identical), tropical clawed frog scrt1 (62% identical), zebrafish scrt1b (60% identical), zebrafish scrt1a (60% identical), Drosophila melanogaster scrt (47% identical), Drosophila melanogaster CG12605 (44% identical), and 3 more. Paralogues in human: SCRT2 (57% identical), SNAI2 (30% identical), SNAI3 (30% identical), SNAI1 (25% identical), HIC1 (21% identical), PATZ1 (20% identical), PRDM1 (20% identical), PRDM10 (20% identical), ZNF410 (18% identical), HIC2 (18% identical), MTF1 (18% identical), ZBTB16 (18% identical), and 24 more.
Diseases named in the same sentence as SCRT1 in open-access papers:
SCRT1 is named in the same sentence as 9 diseases in open-access papers, as found by Europe PMC text mining. Sharing a sentence is not in itself a finding about the gene and the disease. The quoted sentences say what the papers report.
glioma (2 papers, 2022 to 2024). A benign or malignant brain and spinal cord tumor that arises from glial cells (astrocytes, oligodendrocytes, ependymal cells). "Moreover, multivariate Cox regression revealed that CYBB, CD53, SCRT1 and SYP might be independent factors for predicting the prognosis of gliomas." (PMID 35982398, 2022). "Moreover, further multivariate Cox regression analysis revealed that the expression of CYBB (P = 0.00087), CD53 (P = 0.04883), SCRT1 (P = 0.00071) and SYP (P = 0.02491) can be independent factors of the prognosis of gliomas and predict the survival of glioma patients." (PMID 35982398, 2022).
insulinoma (1 paper, 2021). "Next REST was overexpressed in the mouse insulinoma cell line MIN6 and gene expression was analysed by qPCR for Rest, Ins2, Pdx1, Snap25 and Scrt1 three days post infection." (PMID 33888791, 2021).
tumor (3 papers, 2017 to 2024). "Among these 10 genes HDAC1, CASP3, REST, HMG20B, FZD7,GNAI3, FZD1 and EPHB4 had elevated expression in tumor group compared to the normal group, while KCNJ9 and SCRT1 were decreased." (PMID 38629068, 2024).
cancer (2 papers, 2022 to 2024). A tumor composed of atypical neoplastic, often pleomorphic cells that invade other tissues. "For example, SCRT1 (scratch family transcriptional repressor 1), is a recently discovered TF that has been implicated in pancreatic islet cell proliferation and cancer proliferation and metastasis." (PMID 39161769, 2024).
infection (1 paper, 2021). The state of being infected such as from the introduction of a foreign agent such as serum, vaccine, antigenic substance or organism. "At 5 days post-infection, Scrt1 expression was significantly higher when Rest was silenced using the dominant negative mutant." (PMID 33888791, 2021).
SCRT1 also shares sentences with these, for which no sentence is quoted: melanoma (2 papers); autoimmune disease (1); benign neoplasm (1); neuroendocrine carcinoma (1).